IFNG (interferon gamma)
Diseases named in the same sentence as IFNG in open-access papers (continued):
Sharing a sentence is not in itself a finding about the gene and the disease.
ZIKV infection (continued). "Using a qRT-PCR assay, high expression levels of pro-inflammatory cytokine genes, including IL6, IL15, IFNγ, TNFα, CXCL15, IL18, and IL1β, were confirmed in ZIKV-infected placentas, suggesting that ZIKV infection may trigger placental inflammation." (PMID 41263557, 2025). "The intercellular cell adhesion molecule (ICAM-1) a cell surface receptor that can be up regulated by IFNγ, IL1β and TNFα in SCs51 showed increased mRNA expression during culture but was not modulated by ZIKV infection." (PMID 31289325, 2019). "However, DENV/ZIKV coinfection decreased the ability of CD4+ T cells to produce IFNγ+, TNF+, TNF+ IFNγ+, and TNF+ IL2+, compared to DENV and ZIKV infections." (PMID 29282904, 2018). "Thus, we evaluated the capacity of MAIT cells from HIV-1-infected subjects to produce IFNγ in response to ZIKV infection and found that in 5 out of 6 individuals there was no increase in IFNγ production in response to ZIKV infection." (PMID 29357366, 2018). "Although differences in the mouse genetic background (129 versus C57Bl/6) cannot be ruled out as the primary influence behind the severity of neurologic disease, the possible neuroprotective role of IFNγ against ZIKV infection of neural tissue can likewise not be ignored." (PMID 27022155, 2016). "ZIKV infection significantly increased mRNA levels of IFNB, IFNG, IFNL1, and IFNL2/3 in DSCs, but, did not affect the transcriptional levels of IFNA genes." (PMID 36483552, 2022). "Upon polyclonal stimulation ZIKV infection triggered an expansion of CD8+ T cells expressing IL-2, CD107a, Granzyme B and Perforin, but not IFNγ." (PMID 30087337, 2018).
type 2 diabetes (69 papers, 2010 to 2025). "Chronic exposure of islets to the inflammatory cytokines interleukin-1 beta (IL-1β), tumor necrosis factor-alpha (TNF-α) and interferon-gamma (IFN-γ) is associated with β-cell destruction and decreased secretory parameters in both Type 1 and Type 2 Diabetes." (PMID 28893192, 2017). "Some studies have already reported a correlation between NK cell activity, represented by interferon-gamma secretion, and benign diseases such as type II diabetes and herpes zoster, as well as smoking, unhealthy metabolic status, and physical inactivity." (PMID 38674146, 2024). "Consistent with this, it has been reported that IFNg decreased in the blood of sedentary men after 24 weeks of exercise and in men diagnosed with type 2 diabetes who underwent 8 weeks of aerobic exercise." (PMID 39058075, 2024). "Consistently, S-reactive CD4+T cells in participants with type 2 diabetes exhibited significantly lower expression of IFNγ, the defining cytokine for Th1 response following the first dose." (PMID 36304475, 2022). "Specifically, the proportion of CoronaVac vaccinees harbouring S1-reactive IFNγ+CD4+T cells was significantly reduced in participants with type 2 diabetes (p=0.02) after adjustment for BMI." (PMID 36304475, 2022). "Positive CD4+T cell response was defined as the presence of TNFα and/or IFNγ production following peptide stimulation and similar responses were observed between participants with type 2 diabetes and HCs." (PMID 36304475, 2022). "Two clinical studies reported increased serum levels of anti-inflammatory cytokines (IL-4 and IL-10) and decreased levels of TNF-α, IFNγ, IL-12, and IL-6 in females with type 2 diabetes who received 8 weeks of daily NUTRIOSE® supplementation (10 g/day) versus baseline levels." (PMID 37836513, 2023). "Furthermore, among those with detectable S1-reactive CD4+T cell responses, the frequency of polyfunctional CD4+T cells which co-produced IFNγ and TNFα was also significantly lower in participants with type 2 diabetes (p=0.005)." (PMID 36304475, 2022). "To further understand how AGEs accelerate diabetic AS, we investigated the plasma level of AGEs, RAGE, T-lymphocyte subsets, and inflammatory cytokines including tumor necrosis factor alpha (TNF-α) and interferon gamma (IFN-γ) in the peripheral blood of elderly patients with type 2 diabetes." (PMID 33817224, 2020). "They found, however, that the A/A genotype was accompanied by lower glucose levels, and concluded that the decreased expression of IFNγ may contribute to downregulation of inflammatory response in patients with type 2 diabetes, which enables better glycemic control." (PMID 30862026, 2019). "In addition, patients with type 2 diabetes show elevated IFNγ circulating levels." (PMID 30519216, 2018). "Studies involving patients with type 2 diabetes have shown that daily γ-oryzanol intake reduces systemic inflammatory markers such as C-reactive protein (CRP), interleukin-6 (IL-6), and interferon-gamma (IFN-γ), indicating its anti-inflammatory efficacy in metabolic contexts." (PMID 41009004, 2025). "Moreover, similar frequencies of CD4+T cells that produced individual cytokines or co-produced TNFα and IFNγ following S1 or S2 peptide stimulation were detected in responders with or without type 2 diabetes." (PMID 36304475, 2022).
eosinophilia (67 papers, 2002 to 2025). "In NLF from infants hospitalized with RSV bronchiolitis, elevated IL33, among other Th2 cytokines and low levels of IFNγ, was detected in the acute phase of the disease, predisposing them to allergic inflammation and favoring eosinophilia." (PMID 36561744, 2022). "Furthermore IL-5 is positively associated with eosinophilia (r = 0.119, p = 0.050), while IFNγ/IL-5 demonstrates an inverse association to eosinophil counts (r = −0.119, p = 0.030)." (PMID 21179211, 2010). "These cells produce transforming growth factor, IFNγ (mediator of fibrosis), IL-4, and IL-5 (mediators of IgE and eosinophilia)." (PMID 39051325, 2024). "Flow cytometry analysis confirmed the reversal effect of anti-IFNγ mAb on Cm-B-cell-mediated eosinophilia reduction." (PMID 37759658, 2023). "As is observed in human LF, B. malayi infected ferrets exhibit an initial mixed Th1/Th2 immune response, as evidenced by increased cytokine transcription (IL-4, IFNγ) and peripheral eosinophilia, followed by later evidence of immunoregulation." (PMID 29601572, 2018). "In our studies, blockade of IL-10 in conjunction with PZQ treatment led to an increase in eosinophilia and adult worm-specific IL-4, IL-5, IFNγ and IL-17A." (PMID 21829367, 2011). "Many immunological correlates of resistance to re-infection in humans have been reported including IL-5 and eosinophilia, mast cells and IFNγ." (PMID 21829367, 2011). "As previously observed, the adoptive transfer of allergen-pulsed mDCs yields robust production of IFNγ and IL-17A and airway neutrophilia along with the typical Th2 cytokines and eosinophilia, a response which more closely resembles the mixed Th1/Th2/Th17 response observed in severe asthmatics." (PMID 21936897, 2011). "Interestingly, we found a significant increase in IFNγ production in both CD8+ and CD4+ T cells in the lungs of IL5Tg mice compared to both WT and Δdbl-IL5Tg mice, suggesting that eosinophilia and reduced tumor burden in IL5Tg mice correlates with increased proportions of IFNγ producing T cells." (PMID 35756626, 2022). "IFNγ monoclonal antibody blockade led to a modest non-significant increase in airway eosinophilia and IL-5+ ILC2s in mice challenged with Alt and CDG." (PMID 33679760, 2021). "Investigation of IFNγ (100 ng/mL; 5.8 nM) in vitro has demonstrated ability to inhibit IL-4-induced CCL26 production from lung epithelial cells; furthermore, IFNγ administered via the airways has demonstrated efficacy in mice at reducing airway eosinophilia." (PMID 27845745, 2016).
sarcoma (66 papers, 2007 to 2025). A usually aggressive malignant neoplasm of the soft tissue or bone. "The increased sarcoma development observed in Csf3r−/− neutrophil-deficient mice was associated with lower levels of IL-12p70 and IFNγ." (PMID 31257026, 2019). "Activation of SMAD3 and AKT, which is triggered by TGFβ signaling to induce collagen expression, was also inhibited by IFNγ in these tumor cells, suggesting that abundant IFNγ reduces TGFβ-mediated collagen expression in sarcoma cells." (PMID 39574893, 2024). "If IFNγ elevation is the true mechanism behind the reduction of collagen density in collagen-rich sarcomas, we should detect a robust IFNγ increase after attIL12-TIL treatment." (PMID 39574893, 2024). "This concept was demonstrated by the addition of recombinant human IFNγ, which abolished collagen expression in 3 independent sarcoma models." (PMID 39574893, 2024). "For chemically induced models, knockout of NLRP3 protects mice from methylcholanthrene-induced sarcoma in NK cells and interferon gamma (IFN-γ)-dependent manner." (PMID 36932407, 2023). "We co-cultured sarcoma cells with NK-92mi cells and assessed for augmentation of interferon gamma (IFN-γ) production by ELISA." (PMID 33859303, 2021). "Similar to NKG2D-CD16, our NKG2D-CD3 construct showed a profound anti-sarcoma activity as revealed by T cell activation, degranulation, IFNγ and Perforin secretion as well as target cell lysis." (PMID 33936075, 2021). "Neutrophil adoptive transfer restored the expression of IL-12p70 and IFNγ in the TME of sarcoma-bearing Csf3r−/− mice." (PMID 31257026, 2019). "In mice, knockout models showed that interferon gamma (IFNγ) and lymphocytes are important in reducing the incidence of carcinogen-induced sarcoma and spontaneous epithelial carcinomas." (PMID 29570634, 2018). "Infact, in a mouse sarcoma model, it has been shown that glucose consumption by tumors can metabollically inhibit T cell responses, impairing glycolytic activity and IFNγ production." (PMID 29515580, 2018). "USP18 expression in tumor cells, such as human sarcoma 2fTGH cells, is not only induced by IFNγ timulation." (PMID 24884733, 2014). "T cells exposed to NLGP-TME proliferated better in presence of ConA, secreted more IFNγ and showed greater lytic ability towards sarcoma cells compared to PBS-TME as a control." (PMID 23785504, 2013). "We next used immunoblotting to examine whether a switch in the balance of TGFβ and IFNγ levels also affected collagen expression in our sarcoma PDX cells." (PMID 39574893, 2024). "In comparative studies we found that 8H8_SDIE triggers profound NK cell functions such as activation, degranulation, secretion of IFNγ and release of NK effector molecules, resulting in potent lysis of different sarcoma cells and primary sarcoma cells derived from patients." (PMID 36275693, 2022). "Similarly, it was observed that several highly immunogenic and poorly tumorigenic sarcomas from RAG-2 deficient mice were converted into poorly immunogenic, and thus highly tumorigenic, when rendered insensitive to IFNγ." (PMID 35251003, 2022). "Importantly, upon exposure to relevant cytokines, sarcoma-infiltrating DNTαβ cells are the most potent producers of IFNγ compared to other T cell subsets." (PMID 31257026, 2019). "In these sarcoma cell lines, CCKAR regulates collagen expression, which can be markedly decreased by IFNγ elevation." (PMID 39574893, 2024). "In all 3 autologous sarcoma PDX/TIL pairs, coculture of PDX-derived cells with autologous attIL12-TILs dramatically stimulated IFNγ and granzyme B production." (PMID 39574893, 2024). "The suppression of IFNγ signaling by endogenous DUX4 in FSHD muscle cells and the CIC-DUX4 fusion protein in sarcomas provides support for the biological relevance of these findings." (PMID 37092726, 2023).
sarcoma (continued). "Analysis of IFNγ secretion into culture supernatants of PBMC and sarcoma cell lines by Legendplex assays showed an increase in cytokine release after treatment with 8H8_WT with a significantly higher effect upon incubation with 8H8_SDIE." (PMID 36275693, 2022). "Next, we studied antigen specific T cell response, by assessing their ability to secrete/express IFNγ from T cells present in MNCs from blood, spleen, TDLN, VDLN and tumor of day 21 sarcoma bearing mice." (PMID 23326300, 2013). "Importantly, 14 genes involved in the interferon gamma response were upregulated including HLA-B, HLA-C, PD-L1, IL2RB and TNFAIP6, suggesting the reprogramming of the immune microenvironment of sarcoma cells on chidamide inhibition." (PMID 33637599, 2021). "Alternatively, when glycolysis was inhibited in CD8+ T cell using 2-deoxy-D-glucose (2-DG) in the mouse sarcoma model, interferon gamma (IFNγ) but not Interleukin-2 (IL-2) production was inhibited." (PMID 34268109, 2021). "Further, the cytotoxic capacity of PBMC from STS patients was analyzed by co-culturing of PBMC from STS patients and healthy donors with sarcoma cells (RD-ES, SaOs, and SW1353) in the presence of NKG2D‐CD3/CD16 for 24 h followed by intracellular staining for Perforin and IFNγ." (PMID 33936075, 2021). "Gene set variation analysis (GSVA) performed on differentially expressed genes for each cluster showed the enrichment of IFNγ signaling and IL-12 signaling mediated by STAT4 in clusters enriched in Csf3r+/+ sarcomas (clusters 2 and 4), in line with data obtained by flow cytometry." (PMID 31257026, 2019). "Some sarcoma subtypes such as synovial sarcoma and myxoid/round cell liposarcoma characterized as “cold” tumours without high expression of MHC-I and T-cells infiltration, may turn into hot tumours by IFNγ and thus may benefit from combination treatment with IFNγ and other immunotherapy strategies." (PMID 36686827, 2022). "It is of interest that all sarcoma subtypes included in our study expressed PSME1 to a variable extent, while neoadjuvant chemotherapy or treatment with interferon gamma is not standard practice in our hospital." (PMID 27733900, 2016). "In line with TNF-pretreatment of pediatric sarcoma cell lines not promoting anti-tumor activity of unspecific PBMCs, TNF-pretreatment of A673 and TC32 did not enhance IFNγ release of unspecific CD8+ T cells, further indicating that TNF does not promote MHC-I independent cytotoxicity." (PMID 39723214, 2024). "Besides, sarcoma cells from mice lacking IFNAR1 and IFNGR1 were only rejected when sensitivity to IFNγ was restored, not to type I IFN." (PMID 35251003, 2022).
schistosomiasis (64 papers, 2005 to 2026). An infectious disease caused by parasitic trematodes of the genus Schistosoma that colonize human blood vessels and release eggs that can cause granulomatous reactions leading to acute (swimmer's itch or acute schistosomiasis syndrome) or chronic disease. "This study is also, to the best of our knowledge, the first to support a genetic association between IFNG rs2069727 and infection with Schistosoma, and the first to identify an association between schistosomiasis risk and the IFNG gene." (PMID 35759449, 2022). "We also identified a novel association between the IFNG gene and schistosomiasis susceptibility, as IFNG rs2069727*G was found here to be associated with increased risk of infection." (PMID 35759449, 2022). "In addition, we identify novel dominant protective and risk alleles at IL4 rs2070874*T and IFNG rs2069727*G, respectively, for urogenital schistosomiasis and significantly associate the IFNG gene with schistosomiasis susceptibility for the first time." (PMID 35759449, 2022). "If Sm-p40234-246 RI drives the pro-Th1/Th17 response observed in severe schistosomiasis, its neutralization should reduce the production of Th1/Th17 signature cytokines, namely interferon gamma (IFN-g) and IL-17." (PMID 39661861, 2024). "For instance, peripheral blood mononuclear cells isolated from individuals, who are considered naturally resistant to schistosomiasis, produce high levels of interferon-gamma (IFN-ɣ) when stimulated with schistosome antigen." (PMID 26945988, 2016). "However, at the 52-week secondary outcome timepoint, we found higher BCG-specific IFNγ responses in the schistosomiasis-endemic rural compared with the urban setting (1·70 [1·21–2·38])." (PMID 39424574, 2024).
Listeria infection (63 papers, 2005 to 2025). "All five patients had predisposing factors for listeriosis, including corticosteroid (n = 3), targeted therapy (n = 2), pregnancy (n = 2) and anti-interferon gamma autoantibody (n = 1)." (PMID 35572995, 2022). "As depletion of IFNγ in infected Il15ra-/- mice rendered them susceptible to low-dose Listeria infection, it is possible that the DCs are a potential source of early IFNγ in the spleens of Il15ra-/- mice." (PMID 34956227, 2021). "The role of IFNγ in the context of Listeriosis is well-established, as evidenced by the increased susceptibility of mice deficient in either IFNγ or the IFNγ receptor." (PMID 30475900, 2018). "Given that the two genotypes exhibited equal numbers of viable counts in liver homogenates during listeriosis, the increase in IFNγ was likely to be the attempt of properdin-deficient mice to counteract M2-type activity, which is detrimental in listeriosis." (PMID 24728387, 2014). "In fact, the case of listeria bacteremic meningitis (case 5) was the first report of listeriosis in a patient with anti-interferon gamma autoantibody in the literature." (PMID 35572995, 2022). "Conversely, in the miR‐146a KO mouse model, a cell‐intrinsic increased frequency of double‐producing IL‐17+ IFNγ+ cells was observed among γδ27− T cells in vitro (stimulated with IL‐1β and IL‐23) and in vivo, upon Listeria monocytogenes infection." (PMID 33191519, 2020). "Cao and coworkers demonstrated that miR-1 promotes IFNG- (a.k.a IFN-γ) activated innate response in macrophages during Listeria monocytogenes infection through increasing the expression of Stat1 mRNA." (PMID 32957640, 2020). "Agonist anti‐CD137 (4‐1BB) antibodies promoted the expansion of IFNγ+ Vγ1+ T cells, which protected mice from Listeria infection in an IFNγ‐dependent manner." (PMID 33191519, 2020). "As in the findings reported here, CLP-induced mortality and serum cytokine levels increased in co-housed mice, as did IFNγ production by T cells in response to Listeria infection." (PMID 33329524, 2020). "In a model of Listeria monocytogenes infection, IFNγ downregulates expression of CXCR2 (the only receptor for CXCL2 in mice) on neutrophils, thereby curtailing their recruitment to the site of inflammation." (PMID 30012158, 2018). "In contrast, in experimental Listeria monocytogenes infection, the expression of IFNγ by CD4+ T cells was negatively regulated by IFNγR." (PMID 28671989, 2017). "For example, IFNγ-deficient and perforin-deficient mice exhibit altered expansion, contraction and immunodominance of Ag-specific CD8 T cells during Listeria infection." (PMID 24854422, 2014). "The findings of the present study substantiate this notion by demonstrating that IL-15 can elicit, independently of IL-15Rα, innate immune responses following Listeria infection that involve early IFNγ production necessary for pathogen control by sources other than NK cells." (PMID 34956227, 2021). "While the levels of IFNγ in the spleen was comparable between WT and Il15ra-/- mice following Listeria infection, WT mice displayed a 4-fold higher level of IFNγ in the serum, which is obviously derived from NK cells but seems dispensable for bacterial control." (PMID 34956227, 2021). "T‐bet deficiency was found to significantly reduce IFNγ expression by peripheral γδ27+ T cells both in vitro and in vivo upon infection with murid herpes viruses, while also impairing IFNγ production by γδ27−CCR6+ T cells stimulated with IL‐1β or IL‐23 in vitro or during Listeria infection in vivo." (PMID 33191519, 2020). "The synergistic effect of functionally abnormal IL-12p40 allele and high levels of IL-10 production in response to IFNγ may help explain how BTBR mice can both express higher IL-12(p40) and IL-12(p70) than their C57 counterparts, but also be more susceptible to Listeriosis." (PMID 24062633, 2013).